MIR4509-2 (microRNA 4509-2)
Synonyms: hsa-mir-4509-2
Gene: MicroRNA gene on chromosome 15 (28,426,491 to 28,426,584, forward strand). Ensembl gene ENSG00000266039.
Homologues: Paralogues in human: MIR4509-1 (100% identical), MIR4509-3 (100% identical).